ADAM33 (ADAM metallopeptidase domain 33)
Diseases named in the same sentence as ADAM33 in open-access papers (continued):
Sharing a sentence is not in itself a finding about the gene and the disease.
asthma (continued). "The ADAM33 gene may interact with other genes in its role in asthma pathogenesis." (PMID 38396994, 2024). "On the contrary, the biological role of ADAM-33 in asthma pathology remains unknown." (PMID 34204767, 2021). "Several ADAM33 protein isoforms are expressed in human embryonic bronchi and surrounding mesenchyme, and its “reactivation” in adult ASM may explain its genetic association with asthma and bronchial hyper-responsiveness." (PMID 32509793, 2020). "These properties of ADAM33 suggest that it might play a role in progression of asthma." (PMID 29588858, 2018). "Finally, a genomic linkage between certain genes (like coding for the Disintegrin and Metalloproteinase domain containing protein 33, ADAM 33) in certain families with high prevalence of asthma have been suggested to implicate a genetically inherited mechanism." (PMID 28342137, 2017). "However, only ADAM33 and GPRA were associated with an increased incidence of development of asthma." (PMID 27293973, 2016). "While specific expression of human sADAM33 might have been preferred in pulmonary mesenchymal cells that are the main site of ADAM33 expression, the advantage of lung epithelial expression was that sADAM33 was released into the airway lumen, as observed in human asthma." (PMID 27489884, 2016). "Six SNPs (F+1, L−1, S2, T1, T2 and T+1) in ADAM33 were reported to have significant association in seasonal allergic rhinitis (SAR) induced by Japanese cedar pollen, while three SNPs (T1, T+1 and V4) were reported to be associated with AR or concomitant AR and Asthma in a Chinese population." (PMID 24751681, 2014). "However, certain studies in other populations were not able to confirm the association between ADAM33 polymorphisms and asthma." (PMID 24141861, 2013). "The association of ADAM33 with asthma has been confirmed in some studies, but not all." (PMID 18560587, 2008). "Indeed, ADAM33 SNPs that have been associated with asthma are not the SNPs defining protective and risk haplotypes for psoriasis." (PMID 17878941, 2007). "discover that overexpression of soluble ADAM33 promotes the hypercontractile phenotype of rat ASMCs and significantly enhances the activation of the Rho/ROCK pathway, leading to AHR in asthma." (PMID 41426510, 2025). "We did not examine the effects of other ADAM33 polymorphisms that may be relevant for asthma." (PMID 36766510, 2023). "These were in loci previously associated with asthma exacerbations (GSDMB, RAD50, HLA‐DQB1, ADAM33, VDR, and CDHR3) or moderate‐to‐severe asthma (IKZF3, TSLP, MUC5AC, C11orf30, SMAD3, and WDR36)." (PMID 35754128, 2022). "Previously, one study reported an inverse correlation between ADAM33 protein levels in bronchoalveolar lavage fluids and FEV1 in patients with asthma." (PMID 30186568, 2018). "Although a previous report had failed to observe changes in ovalbumin-induced airway responses in Adam33–/– mice, we investigated effects of HDM extract as a common human aeroallergen to model more closely human asthma." (PMID 27489884, 2016). "By the fact that insulin infusion suppresses the expression of IL-4, ADAM-33, LIGHT, and LTBR and the plasma concentrations of NOM and MMP-9, the efficacy of insulin in the treatment of asthma needs to be assessed." (PMID 25642424, 2015). "Insulin decreased mRNA expression of IL-4, ADAM-33, and LTBR (lymphotoxin beta receptor), which are all potentially involved in pathogenesis of asthma." (PMID 26783384, 2015). "Asthma is believed to have a strong genetic background, and hundreds of genes have been identified to be related with asthma, including GSTM1, IL10, CTLA-4, SPINK5, LTC4S, IL4R, and ADAM33." (PMID 24790987, 2014). "Among the cross-referenced genes were several known to be high priority candidate genes in both asthma and hypersensitivity, including GSTP1, ADAM33 and ADRB2." (PMID 23190421, 2012). "However, in some studies the association between ADAM33 polymorphisms and asthma susceptibility could not be confirmed." (PMID 19284602, 2009).
asthma (continued). "Despite those findings, no asthma therapy targeting ADAM33 has been so far developed, which indicates the necessity to perform more research on this topic." (PMID 38396994, 2024). "A recent case-control study has also suggested that SNPs from the ADAM33 (V4 [rs2787094], T1[rs2280091], S2[rs528557]) and AQP5 genes (rs3736309) were specific markers for asthma and COPD, respectively, that may be used to predict individual predisposition." (PMID 35629128, 2022). "Moreover, ADAM33, TGF‐β1 and YKL‐40 are the candidate genes for asthma in the context of airway remodelling." (PMID 34939316, 2022). "Asthma patients with persistent airflow limitation showed higher airway and systemic biomarkers of T2 inflammation (e.g., blood and BAL eosinophilia and circulating periostin), increased blood neutrophil counts, and serum concentration of ADAM-33." (PMID 34204767, 2021). "Other inflammatory mediators, which play a role in asthma, include matrix metalloproteinases (MMP), including MMP-9 and ADAM-33 (a disintegrin and metalloproteinase-33); chemokines including eotaxins, RANTES, and MCP-1; chemokine receptors, CCR-3 for eotaxin, CCR-5 for RANTES, and CCR-2 for MCP-1." (PMID 25642424, 2015). "We investigated the expression of ADAM33 protein in bronchial biopsy tissues from 27 patients with asthma and 7 nonasthmatic controls." (PMID 24817794, 2014). "Genotype frequencies of ADAM33 polymorphisms in dominant model in PER patients with and without asthma." (PMID 24751681, 2014). "Before the advent of genome-wide association studies (GWAS), ADAM33, ADRB2, CD14, MS4A2 (alias FCER1B), IL13, IL4, IL4R, and TNF constituted the most replicated non-HLA candidate genes with asthma and related traits." (PMID 24039878, 2013). "Nevertheless, the demonstration of ADAM-33 implication in pathological processes leading to an asthma phenotype is still not fully accomplished." (PMID 20034386, 2009). "Molecular mechanisms and exact roles of ADAM-33 in the pathological process leading to asthma are therefore not yet fully elucidated." (PMID 20034386, 2009). "Furthermore, hyper-methylation on ADAM33 in bronchial epithelial cells is strongly associated with BHR, irrespective of asthma status." (PMID 27658857, 2016).
allergic rhinitis (10 papers, 2007 to 2025). Inflammation of the nasal mucous membranes caused by an IgE-mediated response to external allergens. "Our results are in line with what was reported previously that ADAM33 gene is associated with allergic rhinitis patients of Asian and Caucasian origin." (PMID 33922216, 2021). "We also found that ADAM33 T1, T2, and T + 1 genotypes were significantly associated with the IgE levels among allergic rhinitis patients." (PMID 33922216, 2021). "In order to validate our hypothesis that ADAM33 genetic variants are associated pulmonary allergic diseases, we included more 95 genomic sample from allergic rhinitis patients." (PMID 33922216, 2021). "We found that the ADAM33 genotype is strongly associated with the allergic rhinitis." (PMID 33922216, 2021). "For further validating our hypothesis, we tested the association of the ADAM33 genotype with allergic rhinitis." (PMID 33922216, 2021). "The aim of the present study was to determine whether ADAM33 SNPs are associated with allergic rhinitis (AR) and allergic asthma (AS) in a Chinese Han population." (PMID 18778489, 2008). "An association of ADAM33 with allergic rhinitis has also been reported in the Japanese population." (PMID 17878941, 2007). "Previous reports revealed that several genetic variants of candidate genes, such as ADAM33, IL4, MRPL4, and TNFA, are positively associated with susceptibility to allergic rhinitis." (PMID 26177022, 2015).
chronic obstructive pulmonary disease (9 papers, 2013 to 2025). A chronic and progressive lung disorder characterized by the loss of elasticity of the bronchial tree and the air sacs, destruction of the air sacs wall, thickening of the bronchial wall, and mucous accumulation in the bronchial tree. "In studies of CAD and chronic obstructive pulmonary disease, ADAM33 was related to both all-cause and cardiovascular-related mortality in 1,390 subjects followed for 18 years." (PMID 27187494, 2016). "The ADAM33 gene is associated with the pathophysiology of Chronic Obstructive Pulmonary Disease (COPD) and atherosclerosis." (PMID 23861802, 2013). "Subsequent studies have linked polymorphisms in ADAM33 to airway hyperresponsiveness and airway inflammation in Chronic Obstructive Pulmonary Disease (COPD), and to accelerated lung function decline and COPD development in the general population." (PMID 23861802, 2013). "For example, among the 4 chronic obstructive pulmonary disease (COPD)–associated proteins shown in the network, TGFB1 is the direct target of HCoV-229E, and all 4 proteins (TGFB1, DEFB1, SNAI1, and ADAM33) interact with at least 1 SARS-CoV-2 target protein." (PMID 33156843, 2020).
breast carcinoma (7 papers, 2009 to 2025). "However, an investigation of 212 breast cancer samples indicated that ADAM33 is silenced by DNA hypermethylation in breast cancer and that low ADAM33 level is associated with short overall and metastasis-free survival." (PMID 36977901, 2023). "After confirmation of the specificity and positivity of the selected monoclonal antibody (mAb) for ADAM33 using our first cohort of 44 breast cancer patients, we decided to evaluate the protein expression of ADAM33 in a different cohort of patients." (PMID 28294120, 2017). "In order to establish a scoring system for the immunoreactivity of ADAM33, an IHC assay with 44 paraffin-embedded breast cancer samples was conducted." (PMID 28294120, 2017). "Using this approach, we find three different scores for ADAM33 in our breast cancer samples: 2 (weak), 3 (intermediate) and 4 (strong), according to the staining intensity." (PMID 28294120, 2017). "In the present study, we have produced monoclonal antibodies against the ADAM33 protein and have investigated the role of ADAM33 protein in breast cancer." (PMID 28294120, 2017). "The breast cancer samples that were ER+/PR+ had ADAM33 scores of 4, while the BLBC and TNBC subclasses showed low expression of ADAM33 (score of 2) (p < 0.001)." (PMID 28294120, 2017). "The analysis of the ADAM33 protein profile in breast cancer was performed in 212 new samples that were part of a tissue microarray (TMA)." (PMID 28294120, 2017). "We showed here for the first time that ADAM33, in combination with currently available biomarkers, may be a novel molecular marker to better ascertain the prognosis of breast cancer." (PMID 28294120, 2017). "The aim of the current study was to produce a monoclonal antibody against ADAM33 to evaluate ADAM33 protein expression in breast cancer and to determine its correlation with the clinicopathological features and the prognosis of patients with breast cancer." (PMID 28294120, 2017). "Then, with these results, it is possible to suggest that the ADAM33 protein might be further investigated as a biomarker in breast cancer." (PMID 28294120, 2017). "In that regard, the ADAM33 gene is silenced by DNA hypermethylation in breast cancer, which suggests that ADAM33 might be useful as a molecular marker." (PMID 28294120, 2017). "In parallel studies for downregulated genes, we were able to identify seven genes with mutations in colon cancer (DPP10, PCSK2, ADAM33, RELN, CAPN13, ADAMTS1 and ADAMTS15), and five genes with mutations in breast carcinomas (MASP3, ABHD12B, TLL1, CPA3 and DPP6)." (PMID 24243807, 2013). "ADAM33 promoter hypermethylation was observed in 29 of 72 (40.3%) breast cancer specimens." (PMID 19267929, 2009). "Moreover, LumA and LumB breast carcinomas showed a strong signal for ADAM33." (PMID 28294120, 2017). "Therefore, it is a plausible hypothesis that in the metastatic breast cancer cell line MDA-MB-231 the epigenetic silencing of ADAM33 may be important in the invasion process." (PMID 28294120, 2017). "Here, we compare clinicopathological information and the expression of a panel of IHC markers (ER, PR, HER2, EGFR, CK 5/6, CK14, CK17, c-Kit and Ki67) with the ADAM33 protein scores to determine whether ADAM33 protein is clinically efficient as a prognostic or predictive marker for breast cancer." (PMID 28294120, 2017). "In addition to, the absence or low expression of ADAM33 protein might contribute to an increase in aggressiveness and metastases, which shows that ADAM33 may play an important role in breast cancer biology." (PMID 28294120, 2017). "We selected breast cancer cell lines that are positive (PMC42, MCF7 and SKBR3) or negative (MDA-MB-231 and MDA-MB-436) for ADAM33 protein based on ADAM33 gene amplification by RT-PCR." (PMID 28294120, 2017).
breast carcinoma (continued). "The mAb selection was based on the reactivity and specificity of the mAb to ADAM33 according to Western blotting and immunocytochemical assays using human breast cancer cell lines that are positive or negative for ADAM33." (PMID 28294120, 2017). "The importance of ADAM33 in TNBC and BLBC is clear and could improve our knowledge of the most aggressive breast cancer subtypes." (PMID 28294120, 2017). "We observe the absence of ADAM33 in breast cancer cell lines, and then we consider the possibility that had a negative tumor (score 0)." (PMID 28294120, 2017). "In this study, we explored the involvement of ADAM33, another ADAM family member, in breast cancer." (PMID 19267929, 2009). "On the contrary, no signal was observed in invasive breast cancer cell lines (MDA-MB-231 and MDA-MB-436) that are negative for ADAM33." (PMID 28294120, 2017).
Allergy (5 papers, 2008 to 2022). An allergy is an immune response or reaction to substances that are usually not harmful. "Our PheWAS indicated that ADAM33 is a risk locus with multiple variants associated with allergy-related phenotypes: MEF240%, allergic bronchitis, and wheezing-eczema comorbidity." (PMID 27624002, 2016).
rhinitis (5 papers, 2008 to 2026). An inflammation of the mucous membrane lining the nose, usually associated with nasal discharge. "We have previously shown that polymorphisms in the ADAM33 gene are associated with adult allergic asthma and rhinitis in a Chinese Han population." (PMID 20003279, 2009). "Some allelic variants of genes were found to be associated with conjunctivitis (FLG), rhinitis (KIF3A), bronchial asthma (IL5RA) comorbidities and high IgE levels (ADAM33)." (PMID 42039188, 2026). "Actually, we did not found such relation of ADAM33 polymorphism and rhinitis severity in patients with mite-sensitized PER." (PMID 24751681, 2014).
allergic asthma (4 papers, 2008 to 2025). A asthma with a basis in a pathological type I hypersensitivity reaction. "In an experimental model of allergic asthma utilizing rats, the silencing of ADAM33 has been proven to decrease the proliferation of ASMCs while concurrently enhancing apoptosis." (PMID 41426510, 2025).
atherosclerosis (4 papers, 2013 to 2025). A disease characterized by the build-up of fatty material and calcium deposition in the arterial wall resulting in partial or complete occlusion of the arterial lumen. "Moreover, in atherosclerosis, ADAM33 expression in vascular lesions appears to inhibit smooth muscle cell migration, highlighting a potential protective role in vascular remodeling." (PMID 41373738, 2025). "Given the increased ADAM33 expression in smooth muscle cells in atherosclerosis and following our hypothesis that overexpression of ADAM33 may lead to the pathological events, subjects at risk may receive tailored therapy with a special target on ADAM33 levels or activity." (PMID 23861802, 2013).
breast tumor (4 papers, 2009 to 2024). "We used 212 breast tumor samples and lower levels of ADAM33 were correlated with TNBC and basal-like markers." (PMID 28294120, 2017). "Using RT-PCR followed by Southern blotting hybridisation, we evaluated ADAM33 mRNA expression in a panel of 20 breast tumour cell lines, normal breast tissue and a normal breast cell line (HB4a)." (PMID 19267929, 2009). "We also used 5-aza-2'-deoxycytidine (5azadCR) treatment and DNA bisulphite sequencing to study the promoter methylation of ADAM33 in breast tumour cell lines." (PMID 19267929, 2009). "The expression analysis of ADAM33 in breast tumour cell lines by RT-PCR revealed gene silencing in 65% of tumour cell lines." (PMID 19267929, 2009). "First, we analysed ADAM33 expression in breast tumour cell lines by RT-PCR and western blotting." (PMID 19267929, 2009). "In the present study, we investigated whether the ADAM33 gene in breast tumours is regulated by epigenetic mechanisms such as DNA methylation." (PMID 19267929, 2009). "Using MSP, we detected ADAM33 promoter hypermethylation in 40% of primary breast tumour samples." (PMID 19267929, 2009). "To investigate the mechanism of ADAM33 transcriptional silencing, we treated MDA-MB-435, MDA-MB-436 and MDA-MB-231 breast tumour cell lines with the demethylating agent 5'-aza-2'deoxycytidine (5-azad-CR)." (PMID 19267929, 2009).
eosinophilia (4 papers, 2016 to 2024). "Moreover, a significant positive interaction between eosinophilia and the allele was observed and a univariate analysis identified the ADAM33 T2 allele as a risk marker for patients with eosinophilia and subsequent exacerbations." (PMID 38396994, 2024). "On the other hand, an analysis of an independent cohort of asthmatic patients showed the association between the ADAM33 T2 A allele and higher blood neutrophil counts only in patients with eosinophilia and not in the general group." (PMID 38396994, 2024). "Blood eosinophilia was positively correlated with the serum concentrations of periostin (r = 0.35, p < 0.05), IL-6 (r = 0.49, p < 0.05), IL-10 (r = 0.66, p < 0.05), IL-12p70 (r = 0.39, p < 0.05), and ADAM33 (r = 0.59, p < 0.05)." (PMID 36835202, 2023). "Enhanced expression of inflammation and remodeling genes in the Ccsp/ADAM33 mice was accompanied by increased airway resistance, as measured by BHR in response to methacholine, and accompanied by BALF eosinophilia." (PMID 27489884, 2016).